INS (insulin)
Diseases named in the same sentence as INS in open-access papers (continued):
Sharing a sentence is not in itself a finding about the gene and the disease.
Obesity (continued). "It has been extensively researched as a model mechanism for anti-obesity effect, including improved insulin sensitivity by aerobic exercise training." (PMID 36461131, 2022). "Interactions between mitochondria and the endoplasmic reticulum, known as MAMs, are altered in the liver in obesity, which contributes to disruption of the insulin signaling pathway." (PMID 36615754, 2022). "Prior to the exercise intervention (at baseline), participants of the current study showed a comparable central insulin response in the right putamen as the participants with overweight and obesity." (PMID 36134657, 2022). "Excess lipids and impaired lipid storage are partly responsible for obesity; thus, fatty acids affect insulin signaling pathways." (PMID 36232527, 2022). "In summary, these data suggested that APC ameliorates obesity through increasing insulin sensitivity." (PMID 35017472, 2022). "Insulin (basal or rapid acting) was more often prescribed for patients with overweight or obesity, whereby the latter showed the highest requirement of total insulin units per day." (PMID 35663318, 2022). "Here, we review the links between obesity, metabolic dysregulation, insulin, and cancer, with an emphasis on current investigational metabolic adjuncts to standard-of-care cancer treatment." (PMID 35244142, 2022). "The two overweight/obesity groups differed also somewhat with respect to fasting insulin and HDL-cholesterol." (PMID 35228658, 2022). "The earliest metabolic changes that we observed in Batf3-/- mice were increased serum insulin and total cholesterol, which preceded impaired intestinal barrier function, obesity, and changes in lamina propria immune composition." (PMID 35812447, 2022). "Dysfunctional insulin rhythmicity can occur from a variety of insults (i.e., obesity, auto-immune disorders, toxins, trauma, stress etc.)that lead to inflammation of this network." (PMID 35163806, 2022). "The results showed low levels of insulin/adiponectin signaling in the endometria from women with obesity, IR and PCOS compared with the control group." (PMID 35409282, 2022). "According to these results, in a recent multidisciplinary study, in vivo selenite vs. in vitro selenite supplementation have been found to show different effects on WAT-insulin sensitivity during obesity and high-fat diet exposure." (PMID 36079831, 2022). "Lipids play critical roles in several major chronic diseases of our times, including those that involve inflammatory sequelae such as metabolic syndrome including obesity, insulin sensitivity, and cardiovascular diseases." (PMID 35358512, 2022). "In this study, metformin increased whole body insulin-stimulated glucose uptake, but the effect was exclusively observed in patients with T2D and obesity, highlighting the paradoxical effects of metformin in lean vs. obese individuals." (PMID 35890085, 2022). "Nevertheless, many cohort studies have reported that some individuals with obesity remain insulin sensitive and are metabolically “healthy” despite similar total fat mass." (PMID 34985174, 2022). "In the present study, the oral administration of Pep19 successfully attenuated body-mass gain and improved the relation between circulating insulin and peripheral insulin sensitivity (disposition index) in a mice model of diet-induced obesity." (PMID 35456900, 2022). "Mice with PAI-1 deficiency, either through gene knockout or the use of a PAI-1 inhibitor, are protected from obesity including hyperglycemia and hyperinsulinemia and demonstrate improved insulin sensitivity." (PMID 35883605, 2022). "Skeletal muscles play a major role in movement and fat catabolism, but the insulin resistance that comes with obesity makes it difficult to fulfill these tasks." (PMID 36144258, 2022).
Obesity (continued). "Skeletal muscle from individuals with obesity exhibits mitochondrial impairments, oxidative stress, ectopic lipid accumulation, and insulin resistance that are believed to contribute to obesity‐related comorbidities (Blüher, 2019)." (PMID 36541258, 2022). "Nevertheless, higher protein intake is thought to increase insulin and insulin-like growth factor-1 (IGF-1) secretion in early childhood, which is associated with early obesity rebound." (PMID 35631148, 2022). "Knockout animal models for NLRP3 and caspase-1 are resistant to the development of obesity and show enhanced insulin sensitivity when compared to controls." (PMID 35164764, 2022). "The microbiota affects glucose and lipid metabolism, obesity-related biochemical parameters, inflammation, and oxidative stress levels, insulin sensitivity, and the intestinal barrier through various signaling pathways." (PMID 35054790, 2022). "Increased level of insulin in obesity stabilized human IL17RA via decreasing the phosphorylation at T780." (PMID 36009523, 2022). "Vitamin E prevents cholesterol accumulation, which leads to obesity through amplification of inflammatory responses and increasing insulin resistance." (PMID 35565860, 2022). "Adolescence is a period of intense growth and endocrine changes, and obesity and insulin-resistance processes during this period have lately been rising." (PMID 36079831, 2022). "Overall, this study showed that the HF before and during pregnancy significantly induced obesity and worsen glucose tolerance, insulin sensitivity, and lipid metabolism in the gestational mice." (PMID 36245521, 2022). "In particular, obesity, age, androgen levels, metabolism and clearance of insulin, and enzymatic degradation of the insulin–receptor complex are perhaps more valuable than insulin itself." (PMID 35456928, 2022). "Our patients also had insulin sensitivity assessed with the Matsuda index, a robust measure to examine abnormalities in glucose metabolism in children and adolescents with obesity." (PMID 35663319, 2022). "An interesting point observed in the present study was the use of lower insulin doses (U/ kg/day) but higher total insulin dose (U/day) in patients with overweight/obesity." (PMID 34983637, 2022). "In our previous study with 12- and 33-week-old Zucker fa/fa rats, we showed that aging and obesity significantly contributed to increased peripheral IR, which further worsened the activation of the hippocampal insulin signaling cascade." (PMID 35589696, 2022). "Both lean and hypothyroid children with obesity had significantly higher levels of fasting insulin and HOMA-IR compared to the control group." (PMID 35501770, 2022). "In conclusion, in Japanese T2DM subjects with less severe obesity, serum SerpinB1 is positively correlated with insulin sensitivity and better blood glucose level." (PMID 36331940, 2022). "We applied a series of MR-based mediation analyses to study the role of hormonal factors—leptin and insulin resistance—in mediating the relationships between obesity and female reproductive health." (PMID 35104295, 2022). "Insulin resistance (IR), also known as damaged insulin sensitivity, is a fundamental aspect of the etiology of T2DM and is also linked to obesity." (PMID 36338341, 2022). "For example, we have already shown such relationships with HOMA-IR as well as insulin area under the curve (AUC) in response to an oral glucose tolerance test in healthy women with obesity." (PMID 35436409, 2022). "Obesity-induced islet inflammation can locally abrogate the islet endocrine cell function and significantly reduce insulin secretion by β cells." (PMID 36066975, 2022). "The severity of disease in the db/db mouse leads to an uncontrolled rise in glycemia, severe depletion of insulin-producing β-cells of the pancreatic islets, obesity at 3 to 4 weeks, and death by 10 months of age." (PMID 36235503, 2022).
Obesity (continued). "High DII facilitates the progression of obesity because it reduces fat oxidation and increases carbohydrate oxidation by increasing insulin secretion, which ultimately increases fat storage." (PMID 36311488, 2022). "In humans, GRB14 gene expression in skeletal muscle decreased after gastric bypass surgery accompanied by improved insulin sensitivity but increased in individuals with obesity." (PMID 35955692, 2022). "IL15 is a myokine that promotes resistance to diet-induced obesity and increases insulin sensitivity and muscle oxidative metabolism." (PMID 36058931, 2022). "During obesity, the maximum expansion capacity of the adipocyte is reached, when ATM produces pro-inflammatory cytokines that affect insulin signaling, causing lipotoxicity and leading to ectopic fat accumulation in tissues like liver and skeletal muscle." (PMID 35681526, 2022). "The MED13/miR-208a system enhances resistance to aberrant cardiac metabolism-mediated obesity and promotes glucose tolerance and systemic insulin sensitivity." (PMID 36613495, 2022). "While PYY is known to reduce appetite and energy intake, delay gastric emptying, and promote insulin secretion, its relationship with obesity and IR remains controversial." (PMID 35334929, 2022). "The interferon regulatory factor 3 (IRF3) plays an important role in obesity and the regulation of insulin sensitivity." (PMID 35456006, 2022). "Another obesity-related hormone is insulin, which partitions circulating fuels into adipose tissues and inhibits the uptake of fuels into non-adipose tissues, resulting in reduced energy expenditure and promotion of calorie intake in HCD." (PMID 36501204, 2022). "IKKε−/− mice were resistant to HFD-induced obesity and chronic inflammation in the adipose tissue and improved insulin sensitivity." (PMID 35662709, 2022). "Recently, several miRNAs have been identified to regulate adipose tissue biology, insulin secretion, and action in the development of obesity and related metabolic complications." (PMID 35565812, 2022). "In the exercise scenario, despite the presence of obesity, in both mice and humans, increased IL-6 levels potentially enhance insulin and glucagon-like peptide-1 (GLP-1) secretion, improving glucose tolerance and insulin sensitivity." (PMID 36452038, 2022). "Inactivation of Wnt/β‐catenin signalling modifies the adipokine‐secretion profile followed by obesity‐induced adipose tissue inflammation, thereby influencing systemic insulin resistance." (PMID 35384342, 2022). "Studies have revealed a positive correlation between parental education and childhood obesity, and obesity was the strongest predictor of insulin sensitivity." (PMID 35719191, 2022). "Obesity is mainly associated with increased levels of free fatty acids (FFA), which increase FFA, reducing insulin sensitivity." (PMID 36522620, 2022). "Globular adiponectin expression in mouse models of obesity or atherosclerosis can ameliorate their detrimental cardiometabolic phenotypes by improving insulin sensitivity and inhibiting the progression of atherosclerotic lesions." (PMID 35789435, 2022). "Studies revealed that IR is frequently characterized by elevated fasting glucose, elevated TG, and obesity in addition to elevated fasting insulin levels (especially increased visceral fat)." (PMID 36203208, 2022). "In response to central insulin, persons with obesity showed altered activity in reward-related brain regions with subsequent effects on eating behavior-related measures (e.g., failure to reduce food craving and hunger)." (PMID 35715625, 2022). "Despite individuals living with obesity having significantly higher blood concentrations of TG, glucose, and insulin, and higher HOMA2-IR scores, these were generally still within the clinically defined ‘normal range’." (PMID 35247847, 2022). "Patients with variants in the non-coding region had a higher percentage of obesity and levels of fasting insulin (62.1% vs. 24.6%, P = 0.001; 80.0% vs. 26.5% P < 0.001)." (PMID 36313763, 2022).
Obesity (continued). "Previously, we have reported that Epac1–/– mice developed more severe obesity, impaired oral glucose tolerance, and insulin resistance when fed the HFD for 8 weeks." (PMID 36329549, 2022). "In rodents, β-adrenergic agonists are effective thermogenic, anti-obesity, and insulin-sensitizing agents that exert their effects primarily through actions in WAT, BAT, and muscle." (PMID 35789435, 2022). "Our previous work in ghrelin receptor knockout mice showed that GHS-R ablation reduces obesity and improves whole body insulin sensitivity in aging." (PMID 36011279, 2022). "Even low-intensity aerobic exercise lasting 60 minutes or longer enhances insulin action in adults with obesity and insulin resistance for at least 24 hours." (PMID 35657123, 2022). "Adiponectin would be expected to prevent obesity and obesity-related diseases by promoting insulin sensitivity and fatty acid oxidation and exerting anti-inflammatory effects." (PMID 36685567, 2022). "During obesity, an increase in plasma insulin concentrations occurs both under basal conditions and postprandially." (PMID 35628332, 2022). "In summary, we provide evidence that IN insulin reduces appetite and food intake and increases positive mood in women with obesity." (PMID 35397638, 2022). "In depth analysis of MK's functional relevance in obesity disclosed impairment of insulin signaling in adipocytes upon MK exposure." (PMID 36204583, 2022). "This study confirms the importance of propionate to inhibit hepatic lipogenesis and improve insulin sensitivity in high-fat diet-induced obesity." (PMID 35571895, 2022). "Those with obesity have been reported to have greater glucose-lowering with thiazolidinediones, which act to improve insulin sensitivity and lipid metabolism by stimulating the nuclear receptor peroxisome proliferator-activated receptor gamma (PPARG)." (PMID 36699039, 2022). "This study aimed to investigate perceptions and experiences of participating in a 12-week exercise intervention designed to study the mechanisms of insulin sensitivity and secretion in young Black SA women with obesity." (PMID 36275440, 2022). "Obesity also reduces the level of adiponectin, a fat factor involved in anti-inflammatory and insulin sensitization, thereby increasing kidney damage." (PMID 35054932, 2022). "IN insulin in the post prandial state reduced cookie intake, appetite and food reward relative to placebo and these effects were more pronounced for women with obesity compared with lean women." (PMID 35397638, 2022). "Animal studies support a role for CD36 in impaired glucose tolerance and insulin signalling in obesity as well as macrophage infiltration into AT and overproduction of inflammatory cytokines and chemokines." (PMID 35348641, 2022). "The obesity phenotype is characterized by structural and functional changes in the skeletal muscle microcirculation which contribute to insulin dysfunction and disturbed glucose homeostasis." (PMID 35055038, 2022). "Obesity promotes disruptions in multiple metabolic pathways, such as up-regulated sex steroid hormones, insulin, inflammatory mediators and lower adiponectin levels, which influence cell division, cell death and healing." (PMID 35120118, 2022). "Aerobic exercise has been extensively studied as a mechanism for anti-obesity effects, including improved insulin sensitivity." (PMID 36461131, 2022). "Little is known of the role of GLP-1 in increasing insulin secretion in a healthy pregnancy, and even less so in pregnancies complicated by obesity and GDM." (PMID 35099411, 2022). "Although the molecular mechanism for SIRT3 regulation of endothelial insulin sensitivity remains to be elucidated, this protective role of SIRT3 in obesity has been observed to be linked with reduced mitochondrial ROS production." (PMID 35369299, 2022). "High doses of MSG administration in neonatal rats lead to induction of obesity, decreased insulin sensitivity, and inflammation in adult Wistar rats." (PMID 36033946, 2022).
Obesity (continued). "T2DM is now being diagnosed more often in children and adolescents with obesity due to β-cell malfunction or unresponsiveness to insulin in the organs; in this vicious circle, the insulin secretion is insufficient to compensate for IR." (PMID 36013384, 2022). "It has been widely described that there are different phenotypes of obesity: metabolically healthy obesity phenotype is characterized by high insulin sensitivity, low prevalence of hypertension and a favorable fasting glucose, lipid, and inflammation profile." (PMID 36235590, 2022). "We demonstrated that a HFD induced obesity and impaired insulin sensitivity in mice, but these detrimental effects were prevented by restricting BCAAs within a HFD." (PMID 35448521, 2022). "In line with this, in another study on adolescent females with obesity, plasmatic glucose, insulin, and HOMA-IR significantly improved after a 12-week jump rope exercise program." (PMID 36364954, 2022). "Compared with healthy lean people, people with obesity have increased basal and postprandial plasma insulin concentrations." (PMID 35054781, 2022). "Unfortunately, we were unable to lend support for the role of hyperinsulinaemia in linking obesity and hyperandrogenism due to a weak insulin exposure instrument." (PMID 35049520, 2022). "In this regard, very recently, the 11BHSD1 inhibitor S-707106 was found to be an effective insulin sensitizer, anti-sarcopenic and anti-obesity drug for patients with Cushing’s syndrome and mHC." (PMID 35054858, 2022). "Increased insula activation by IN insulin was observed in both BMI groups, but effects on appetite and food intake were observed only in women with obesity." (PMID 35397638, 2022). "We observed that pre-pubertal children with obesity and with low z-scores of circulating leptin levels had significantly higher triglyceride, fasting insulin and fasting c-peptide levels compared to children with normal z-scores of circulating leptin levels." (PMID 35677722, 2022). "Initially, factors such as obesity led to insulin resistance, forcing pancreatic beta cells to exert excessive normal action for more insulin to maintain normal glucose levels." (PMID 36187475, 2022). "One study on SAT androgen concentrations found that testosterone is increased and sequestered in adipocytes from men with obesity and insulin-resistant 3T3-L1 cells in vitro." (PMID 35511873, 2022). "The mice exhibit obesity, hyperphagia, transient hyperglycemia, glucose intolerance, and increased plasma insulin." (PMID 35563777, 2022). "The current study reports on a dietary intervention that produces significant obesity but maintains normal insulin action in mice providing some mechanistic understanding of the phenomenon of obesity with preserved insulin sensitivity." (PMID 36394259, 2022). "During obesity, essential AT metabolic regulation and lipid handling are disrupted due to changes in adipokine production, insulin sensitivity, adipogenesis, angiogenesis, and extracellular remodeling." (PMID 35456015, 2022). "Further investigation of the therapeutic potential of IN insulin for weight management in women with obesity is warranted." (PMID 35397638, 2022). "On the contrary, reinstatement of ATG7 expression in the liver limited ER stress and improved insulin activity and systemic glucose tolerance in mice with obesity." (PMID 35093121, 2022). "Obesity-related alterations of insulin/IGF-1 signaling as well as premature aging processes are significantly caused by a prevailing systemic inflammation, the latter being known as ‘inflamm-aging’." (PMID 35628414, 2022). "After 15 weeks of an HFHC diet, the HFHC diet groups demonstrated obesity, hyperglycemia and impaired whole-body insulin sensitivity, elevated liver enzyme levels, and hepatic steatosis." (PMID 36348343, 2022).